SMAD4 (SMAD family member 4)
Diseases named in the same sentence as SMAD4 in open-access papers (continued):
Sharing a sentence is not in itself a finding about the gene and the disease.
pancreatic cancer (continued). "SMAD4 (mothers against decapentaplegic homolog 4), also known as DPC4 (deleted in pancreatic cancer-4), is member of the SMAD protein family." (PMID 38334666, 2024). "(A) Representative H&E staining of pancreatic tumor sections derived from KPC cells of the indicated genotypes, SMAD4 KO (n=12), SMAD4/STAT3 DKO (n=3) and TGFBR2/STAT3 DKO (n=3), where n denotes the number of mice injected." (PMID 38573819, 2024). "While SMAD4 is normally expressed in breast cancer where we have shown that BMP4 has anti-metastatic activity, in colorectal and pancreatic cancers where a pro-tumor role of BMP4 is observed, SMAD4 is mutated or lost in up to 40% of cases." (PMID 38689334, 2024). "(C) Summary of pancreatic tumor development in nude mice by KPC cells of the indicated STAT3, SMAD4, and TGFBR2 genotypes presented." (PMID 38573819, 2024). "This suggests that in pancreatic tumor cells of human origin, too, TAp73 promotes TGF-β signaling through activation of a SMAD4-dependent pathway." (PMID 37568607, 2023). "In pancreatic cancer, a series of SVs, including large deletions, inversions, and translocations, led to the inactivation of CDKN2A/p16 and SMAD4/DPC4." (PMID 37674481, 2023). "The deletion of SMAD4 affected the TGF-β/SMAD4 signaling pathway and made pancreatic cancer more aggressive." (PMID 36672865, 2023). "In the present study, the inhibition of SMAD4 rescued the S100A2-enhanced metastasis and EMT of pancreatic cancer cells." (PMID 37758734, 2023). "SMAD4, also known as deleted in pancreatic carcinoma 4 or DPC4, is located on chromosome 18q21 and inactivated in roughly 55% of pancreatic cancers." (PMID 35155243, 2022). "Meanwhile, the protein expression levels of SMAD2, SMAD3, SMAD4, and p-SMAD2/3 were also detected in the pancreatic cancer cells with the ITGA2 gene silenced." (PMID 35193647, 2022). "Hypoxia increases TGF-β levels in pancreatic cancer cells, and TGF-β in a Smad4-dependent manner increases nestin expression, resulting in increased tumor-cell migration and EMT." (PMID 35625561, 2022).
pancreatic cancer (continued). "A study has revealed that hypoxia induces Fbln5 in a TGF-βRI/ALK5-dependent and Smad4-independent manner, and hypoxia and TGF-β increase the expression of Fbln5 in pancreatic cancer." (PMID 35625561, 2022). "SMAD4, also called SMAD family member 4, Mothers against decapentaplegic homolog 4, or DPC4 (Deleted in Pancreatic Cancer-4) is a central mediator of TGF-β signalling by forming complexes with receptor-activated SMADs (SMAD-2 and -3)." (PMID 35144669, 2022). "In summary, this study provides mechanistic evidence for a tumorigenic role of miR-552 in pancreatic cancer and uncovers a novel FOXM1-miR-552-DACH1/PCDH10/SMAD4 axis that promotes pancreatic cancer progression." (PMID 33867818, 2021). "Functional activation and overexpression of the components of the activin/nodal signaling pathway including Nodal, Cripto-1, FoxH1, Smad2, Smad4, Gdf1, activin, and ACVR1B were detected in primary pancreatic cancer stem cells (CSC)." (PMID 34356885, 2021). "SMAD4 is critical for TGF-β-driven EMT and induces changes in the expression of EMT markers in human pancreatic cancer cells." (PMID 34885065, 2021). "SMAD-4 is a key signal transducer of the TGF-β signaling pathway, and it is inactivated in nearly 55% of pancreatic cancer patients." (PMID 33918146, 2021). "We demonstrate that IPMNs and MCNs are precursors of invasive pancreatic cancer, that alterations in ATM, GLI3, and SF3B1 are present in these lesions, and that SMAD4/TGFBR2 alterations are likely drivers of invasion in a subset of cases." (PMID 32796935, 2020). "High expression of S100A8 and S100A9 was found in the stroma cells, mainly monocytes, of pancreatic cancer, and the number of S100A8 positive stroma cells correlated with the Smad4 status of the tumour." (PMID 32722137, 2020). "In the JNK pathway, SMAD4 inhibits JNK activity by increasing MKP1 levels to reduce VEGF expression, thus attenuating the development of pancreatic cancer cells." (PMID 31684910, 2019). "SMAD4 stands for SMA- and MAD-related protein 4, other names are SMAD family member 4, Deleted in Pancreatic Cancer-4 (DPC4) and Mothers against decapentaplegic homolog 4, SMAD4 is present in all metazoans and is highly conserved between species." (PMID 31867281, 2019). "However, SMAD4 loss does not initiate tumorigenesis in human pancreatic cancers." (PMID 30018740, 2018). "Interestingly, in KP4-4 cells, a SMAD4-depleted pancreatic cancer cell line, the MET phenotype was induced by miR-509-5p but not by miR-1243, suggesting that the mechanism by which the MET phenotype is induced by miR-1243 might depend on the TGF-β signaling pathway." (PMID 28638102, 2017). "The PANCALYZE trail aims to predict the clinical course of pancreatic cancer on the basis of CXCR4, SMAD4, SOX9 and IFIT3 expression." (PMID 28356064, 2017).
pancreatic cancer (continued). "SMAD4 is a core factor of TGF-β signaling, and has been identified as a common tumor suppressor in colon and pancreatic cancers, owing to aberrant protein degradation." (PMID 28827661, 2017). "Smad4 acts as a central mediator in the TGF-β signaling, and its inactivation is relatively specific for pancreatic cancer." (PMID 28794854, 2017). "Transient depletion of Rac1b protein in pancreatic cancer cells by RNA interference increased the extent and duration of TGF-β1-induced phosphorylation of p38 MAPK in a Smad4-independent manner." (PMID 29229918, 2017). "TGFβ1 and S100A8/A9, which share their overall effects on pancreatic cancer cells, mainly inhibit NF-κB and PI3K/AKT in a SMAD4-dependent manner." (PMID 27655713, 2016). "SMAD4 has been shown to influence EGFR and VEGF expression in human normal pancreatic ductal cells (HPDEC) and Hs766T human pancreatic cancer cells." (PMID 24625091, 2014). "The Smad4 gene, also known as tumor suppressor DPC4 (deleted in pancreatic cancer cells), is inactivated in about 55% of PDAC cases, either by homozygous deletion or intragenic mutation with loss of its second allele." (PMID 24325450, 2013). "Many oncogenic molecular pathways including EGF/EGFR, Ras-Raf-MEK, PI3K/Akt, JAK/STAT, p16INK4A/retinoblastoma, Smad4/TGF-β, and hedgehog signaling pathways, have been reported to be involved in the pathogenesis of pancreatic cancer." (PMID 22348037, 2012). "LOH on 18q with SMAD4 is detected in 43% of EUS-FNA specimens from chronic pancreatitis and in 78% of EUS-FNA specimens from pancreatic cancer." (PMID 23197977, 2012). "Smad4 has been shown previously to inhibit VEGF expression and suppress tumorigenicity through inhibition of angiogenic activity in human pancreatic carcinoma cells." (PMID 22507670, 2012). "The inactivation of the tumor suppressor DPC4 (deleted in pancreatic carcinoma, locus 4), also called SMAD4 or MADH4 is most frequently found in ductal pancreatic adenocarcinomas (approx. 50%) and metastatic colon carcinomas (approx. 30%)." (PMID 21492476, 2011). "Because we have previously shown that increased SMAD4 expression at the protein level can be induced by the transfection of WWOX-expressing vector into pancreatic cancer-derived PANC-1 cells, we also examined the SMAD4 expression in these IPMN cases." (PMID 19352382, 2009). "To date, there are many reports regarding the TGF-β signalling pathway in pancreatic cancer (e.g. TGF-β receptor II, Smad2 and Smad4), but only a few deal with this gene’s alterations in pancreatic cancer." (PMID 18475302, 2008). "In pancreatic carcinoma cells BxPC3 and CFPAC-1, Smad4 reexpression also increased constitutive LM-332 expression levels and additionally restored TGFβ induction of LM-332." (PMID 18664273, 2008). "These SMAD-4 independent mechanisms of TGF-β signaling, in pancreatic cancer are not clearly understood." (PMID 18157915, 2007). "For example, Smad4/Dpc4, a signaling molecule of TGF-β- related pathways required for gastrulation and anterior development of the mouse embryo is involved in 50% of pancreatic cancers." (PMID 18030336, 2007). "An example is the observed lack of the suppressor gene DPC4 in pancreatic cancer, which is responsible for the synthesis of the protein Smad-4, which is an effector of TGF-1." (PMID 38672279, 2024). "EMT responses in the Colo357 pancreatic cancer cell line were not affected by RNA interference-induced SMAD4 knockdown." (PMID 39087024, 2024).
pancreatic cancer (continued). "A comparative study of SMAD4/DPC4-negative and SMAD4/DPC4-positive tumours revealed that the presence or absence of SMAD4/DPC4 had a differential impact on the biological behaviour of pancreatic cancer." (PMID 37685308, 2023). "As an example, the Kruppel like factor 5 (KLF5), is a potentially interesting therapeutic target in SMAD4-negative colorectal and pancreatic cancers." (PMID 37377893, 2023). "Our findings add to the evidence that KLF5 is a potentially interesting therapeutic target in SMAD4-negative colorectal and pancreatic cancers, even if transcription factor targeting is still challenging." (PMID 37377893, 2023). "In summary, our work identifies RAB10 as a potentially synthetic lethal gene in SMAD4-negative colorectal and pancreatic cancer cells." (PMID 37377893, 2023). "Moreover, we found that S100A2 is a novel regulatory factor for pancreatic cancer cell metastasis, with SMAD4 being a potential downstream target, and together they form the S100A2/SMAD4 axis to promote cellular invasion and migration." (PMID 37758734, 2023). "For instance, in pancreatic cancer cell lines, deletions in the CDKN2A and SMAD4 genes, both of which are common in pancreatic cancer tumors, have in addition to a direct consequence on the coding gene, a three-dimensional consequence altering the contact domains in the area." (PMID 37457299, 2023). "Our CRISPR genome-wide loss-of-function screen was performed in four nonisogenic colorectal and pancreatic cancer cell lines, two SMAD4-negative and two SMAD4-positive cell lines." (PMID 37377893, 2023). "Altogether, SMAD4 regulated S100A2 function in EMT and the metastasis of pancreatic cancer cells." (PMID 37758734, 2023). "Based on the literature, the role of Smad4 is unclear: researchers have reported its participation in HCC and bone metastases as well as the suppression of other types of cancer, such as colorectal and pancreatic cancer." (PMID 38067256, 2023). "CRISPR-mediated ablation of KLF5, SMAD4, or EGFR in pancreatic tumor cells leads to increased T-cell infiltration and improved combination immunotherapy response with gemcitabine, abraxane, CD40 agonistic antibody, CTLA4-blocking antibody, and PD-1-blocking antibody (named as GAFCP)." (PMID 35159011, 2022). "Here, our findings support that SMAD2/3 mediate oncogenic properties of TGFβ in the absence of SMAD4 in pancreatic tumor cells, by conferring them a collective migratory ability through modulation of Rho/Rac and FAK activities to form FA." (PMID 36207615, 2022). "Previous studies reported that patients without SMAD4 protein expression had a shorter survival time from pancreatic cancer, colon cancer, and esophageal cancer." (PMID 36088360, 2022). "To identify potential immunologic differences between SMAD4-expressing and SMAD4-nonexpressing tumors, we first evaluated the TCGA genomic database of pancreatic cancer patients (N=186)." (PMID 35155243, 2022). "Deletion of SMAD4 would eliminate the canonical TGF-β/SMAD4 signaling pathway and may make pancreatic cancer more aggressive." (PMID 36359832, 2022).
pancreatic cancer (continued). "It has been reported that SIRT1 is overexpressed in pancreatic cancer tissues and is a promoter of the occurrence and metastasis of pancreatic cancer; however, SIRT1 has the opposite effect in oral squamous cell carcinoma, which inhibits EMT through the SIRT1/Smad4/MMP7 pathway." (PMID 34934771, 2021). "A previous study showed that the expression of Smad4 is absent in pancreatic cancer, and its deletion can promote the progress of pancreatic cancer and increase the tumor metastasis." (PMID 33794845, 2021). "SMAD4 depletion in the Colo-357 pancreatic cancer cell line with RNAi did not succeed in disturbing EMT responses in those cell lines." (PMID 33918146, 2021). "SMAD4/DPC4, a putative tumor suppressor in pancreatic carcinoma, was mutated or deleted in 55% (5 of 9) of non-functioning pNETs but remained intact in 100% of the less aggressive, functional pNETs (insulinomas, gastrinomas, and VIPnomas)." (PMID 34680266, 2021). "Smad4 is a key mediator for TGFβ, a pro-apoptotic protein involved in pancreatic tumour progression, and tumours without Smad4 expression showed a decreased number of S100A8+ stroma cells." (PMID 32722137, 2020). "In SMAD4-negative pancreatic cancer cells treated with the compound UA62001, the cell cycle was interrupted in synthesis (S) and Gap 2 (G2) – mitotic (M) phases, whereas UA62784 activated CDK1 and induced mitotic cell-cycle arrest and apoptosis." (PMID 32429474, 2020). "The downregulation of SMAD4 counteracts TGF-β-induced cell cycle arrest and apoptosis, but the restoration of this tumor suppressor gene can reverse the invasive phenotype as well as attenuate the proliferation of pancreatic cancer cells." (PMID 32420409, 2020). "In addition, it has been reported that inactivation of SMAD family member 4 (SMAD4) and cyclin dependent kinase inhibitor 2A (CDKN2A) is related to the development of pancreatic cancer." (PMID 32587798, 2020). "Western blot analysis and qRT-PCR indicated that SMAD4 was successfully overexpressed in human pancreatic cancer cells compared to negative control cells." (PMID 31684910, 2019). "BRCA2, Smad4, EGFR genes play important role in pancreatic cancer pathway." (PMID 30792708, 2019). "The blocking of MUC1-CT downstream signaling in SMAD4 - negative pancreatic cancer cell line reduces the effects previously seen in the MUC1-high expressing cells, establishing the importance of MUC1-CT." (PMID 29467938, 2018). "The role of the tumor suppressor mothers against decapentaplegic homolog 4 (SMAD4) has not yet been defined in patients (pts) with advanced pancreatic cancer (aPC)." (PMID 28534865, 2017).